BRCA1 (BRCA1 DNA repair associated)
Diseases named in the same sentence as BRCA1 in open-access papers (continued):
Sharing a sentence is not in itself a finding about the gene and the disease.
breast cancer (continued). "Although the BD-L signature is present in all subtypes of breast cancer, it is significantly higher in BRCA1 mutant primary tumors as compared with sporadic breast tumors." (PMID 24625110, 2014). "Recent studies have shown that in cells lacking BRCA1 mutation, sensitization to treatment with PARP inhibitor can also be achieved in sporadic breast cancers through depletion of BRCA1 due to promoter methylation." (PMID 25026298, 2014). "The present study investigated the correlation between BRCA1/2 mutations and TNBC status in a large series (n=726) of breast cancer patients from Sardinia." (PMID 24944648, 2014). "This indicates a strong association between the presence of methylated BRCA1 promoter in WBC and early onset of breast cancer (p = 0.032)." (PMID 25403427, 2014). "Triple-negative MDA-MB-231, BRCA1-defective HCC1937 and BRCA1-competent MCF-7 breast cancer cell lines were treated with ruthenium(II) complexes." (PMID 24507701, 2014). "To uncover novel biologically significant molecular functions of BRCA1, we tested a panel of 198 approved and experimental drugs to inhibit growth of MDA-MB-231 breast cancer cells depleted for BRCA1 by siRNA." (PMID 25522274, 2014). "As expected, the level of BRCA1 methylation was significantly higher in WBC from breast cancer group than from the carriers." (PMID 25403427, 2014). "The tumor suppressor genes BRCA1 and BRCA2 (Breast Cancer 1 and 2, early-onset) are involved in DNA repair mechanisms and are often mutated in breast cancer." (PMID 25322458, 2014). "The BRCA1 3450del4 founder mutation accounts for 11.5% of unselected ovarian cancers and represents 73% of BRCA mutations and 1.6% of unselected breast cancers in Bogota." (PMID 24742220, 2014). "Specific inhibition of HSP90 in BRCA1-proficient breast cancer cells-induced BRCA1 ubiquitination and proteasomal degradation ultimately resulting in compromised DSB repair by HR." (PMID 24624361, 2014). "Among these 51 cancer genes the most prominent breast cancer genes BRCA1, BRCA2, and Chk2 were present." (PMID 24550935, 2014). "Recent studies in breast cancer models demonstrated an interesting relationship between BRCA1 and stem cell differentiation." (PMID 25216266, 2014). "Deletions of functional copies of MAP2K4 and BRCA1 have also been reported in several breast cancer cell lines." (PMID 25264427, 2014). "The closest correlation is the mutations in the FOX family, in which FOXA1 is somatically mutated in sporadic breast cancer and FOXP1 is germline-mutated in the BRCA1+ family." (PMID 24884718, 2014). "Five female and a male breast cancer patient from 4 different families were heterozygous for the BRCA1 substitution p.Ser36Tyr." (PMID 24695549, 2014). "Interaction between BRCA1 and AhR was enhanced by xenobiotic TCDD in breast cancer cells and BRCA1 was recruited to the promoter regions of CYP1A1 and CYP1B1 along with ARNT/AhR following TCDD exposure." (PMID 24704793, 2014). "A previous study demonstrated that alcohol down-regulated the expression of BRCA1, a potent inhibitor of ERα, thereby contributing to breast cancer." (PMID 25400119, 2014). "In a similar analysis, endometrial cancer was overrepresented in 803 non-BRCA1/2 breast cancer families compared to the general cancer population." (PMID 24851142, 2014). "Methylation of the BRCA1 promoter has been reported in about 10 to 30% of breast cancers and BRCA1-methylated tumors have a BRCA1-like phenotype." (PMID 25416589, 2014).
breast cancer (continued). "Ruthenium treatment upregulated the marker genes involved in apoptosis and cell cycle progression while it downregulated BRCA1 mRNA and replication of BRCA1-defective breast cancer cells." (PMID 24507701, 2014). "BRCA1/2 mutations are most common in TNBC; however, both germline and somatic mutations were observed in all subtypes of breast cancer." (PMID 25475740, 2014). "In this two-stage case-control study with 1,764 non-BRCA1/2 breast cancer patients and 1,623 cancer-free controls, we investigated the contribution of genetic variants of XRCC4 to breast cancer susceptibility in Chinese women." (PMID 25360583, 2014). "The prevalence of BRCA1 LGRs ranges from approximately 6%–27% of all mutations detected in the BRCA1 gene; BRCA2 LGRs play a minimal role in breast cancer." (PMID 25176351, 2014). "Therefore, a more specific epigenetic therapy could be developed for BRCA1-mutated breast cancer." (PMID 24675476, 2014). "Similar to mutations in BRCA1 and BRCA2, the risks associated with monoallelic mutations in PALB2 seem to extend beyond breast cancer." (PMID 25225577, 2014). "Conversely, inhibition of ERK1/2 signaling using pharmacological inhibitors or siRNA also results in the destabilization of BRCA1 protein in irradiated breast cancer cells." (PMID 25174607, 2014). "Lastly, we demonstrated that the BD-L metagene outperforms extant classifiers of BRCA1/2 status in predicting pharmacological response to the drug combination in the breast cancer cell panel." (PMID 24625110, 2014). "Comparing the prevalence of the BRCA1-3’UTR-variant within respective subtypes with controls, Luminal A breast cancer was most strongly associated with the variant by the dominant model (OR = 1.5, 95% CI 1.1-1.9)." (PMID 24915755, 2014). "In this study, we used exome sequencing method to analyze the entire coding genes in the genomes of blood cells in a typical BRCA1+ breast cancer family." (PMID 24884718, 2014). "The dataset included 4,477 BRCA1 mutation carriers, 2,565 BRCA2 mutation carriers, and 47,565 BCAC breast cancer cases." (PMID 25857409, 2014). "The high-risk and well characterized tumor suppressor genes BRCA1 and BRCA2 are thought to be responsible for the majority of hereditary breast cancer, with germline mutations conferring a life-time risk of 55–85% and 35–60% respectively." (PMID 24830819, 2014). "The majority of BRCA1/2-related breast cancers exhibit high grade and are insensitive to most available hormonal or targeted therapeutic agents." (PMID 24962108, 2014). "Lestaurtinib amplifies the ability of the PARP1 inhibitor AG14361 to kill BRCA1 mutant and wild-type breast cancer cells, at least in part, by inhibiting NF-κB signaling." (PMID 24962108, 2014). "The results revealed that the compounds were docked more firmly and inhibited the breast cancer related BRCA1 and BRCA2 oncoproteins and COX-2 and COX-1 inflammatory proteins." (PMID 25254204, 2014). "BRCA1 promoter methylation has been detected in DNA from peripheral blood cells of both breast cancer patients and cancer-free females." (PMID 25403427, 2014). "The present results suggest the presence of a strong link between aberrant methylation of the BRCA1 promoter in WBC and breast cancer –related molecular changes, which indicate the potential predisposition of the carriers for developing breast cancer." (PMID 25403427, 2014). "Lately, BRCA1 promoter methylation has been detected in DNA from both white blood cells and tumor tissues in 3 out of 7 breast cancer patients from breast-ovarian cancer families." (PMID 25403427, 2014). "We have shown that the BRCA1 promoter is methylated in WBC of 14.2% of breast cancer patients and that this methylation is significantly associated with the early onset of the disease." (PMID 25403427, 2014).
breast cancer (continued). "If the same tendency is true for defects in other high penetrance breast cancer genes, tumors from genetically related patients would exhibit related molecular subtypes, as it is the case for BRCA1 and BRCA2 families." (PMID 24479546, 2014). "Family history profiles can predict BRCA1 or BRCA2 mutation, mainly those characterized by first-degree relatives with ovarian cancer or breast cancer along with young age at diagnosis, bilateral occurrence and increased number of affected relatives." (PMID 24591761, 2014). "The first FANCJ mutants to be studied were missense variants (P47A, M299I) identified in individuals with early breast cancer and normal genotypes for BRCA1 or BRCA2." (PMID 25374583, 2014). "Our interest in the use of FTY720 originates from the observations in our preliminary studies showing enhanced sensitivity of a BRCA1 mutant breast cancer cell line to FTY720 (unpublished)." (PMID 24460909, 2014). "We have shown her that healthy women with BRCA1 methylation in their WBC have, besides BRCA1 methylation, modulation in the methylation and expression of other breast cancer-related genes, in addition to the secretion of important cancer- related proteins." (PMID 25403427, 2014). "This variant, first reported in a Swedish ovarian cancer patient with a family history of breast cancer and other malignancies, lies on the BRCA1 coiled-coil domain and was reported to disrupt the interaction between BRCA1 and PALB2." (PMID 24845084, 2014). "Application of this LOH clustering approach to a high-grade breast cancer data set separated tumors into a Lo cluster comprising HER2- and hormone receptor-positive cancers and a Hi cluster comprising TNBCs and BRCA1-associated tumors." (PMID 25093514, 2014). "Results from various studies revealed that 9-44% of sporadic breast cancer samples harbor hypermethylated BRCA1 promoter." (PMID 25403427, 2014). "BRCA1 promoter methylation was examined by methylation-specific PCR in WBC from 155 breast cancer patients and 143 cancer-free females." (PMID 25403427, 2014). "Many of the genes in the RRHGE gene signature are already defined as well-known oncogenes, such as AR, BRCA1, CDK2, and CCND1, besides others, whose differential expression has been associated with the subtypes of breast cancer." (PMID 24563630, 2014). "Several studies have investigated a potential role for BRCA1 inactivation in sporadic TNBC given the similar clinical outcomes and histological characteristics among these cancers and hereditary BRCA1-mutated breast cancers." (PMID 24579064, 2014). "Defects in the BRCA1 or BRCA2 genes are responsible for most hereditary forms of breast cancer and account for as many as 10% of all breast cancer cases." (PMID 25011685, 2014). "Variants in or near the known breast cancer susceptibility loci TERT, ESR1 and 19p13.11 showed strong associations (P <10−6) with at least one of the categories in all subtype analyses in BRCA1 carriers." (PMID 25919761, 2014). "On the basis of the cut-off value ±1.5 fold relative to controls, 16 genes, including BRCA1, were differentially expressed in breast cancer cases and carriers as compared to controls." (PMID 25403427, 2014). "This was further confirmed by showing that the BRCA1 mRNA was significantly lower in the breast cancer group than in the carriers." (PMID 25403427, 2014). "Among BRCA1 mutation carriers, TNBC represents the predominant breast cancer subtype (more than two-thirds of cases)." (PMID 24944648, 2014). "Three previous studies have evaluated the prevalence of BRCA1 and BRCA2 mutations in breast cancer cases in the Colombian population." (PMID 24742220, 2014).
breast cancer (continued). "We examined for interactions between BRCA1 and PTEN loss of expression as PTEN loss is a frequent initiating event in BRCA1-associated breast tumours and is associated with basal-like breast cancer." (PMID 25608477, 2014). "Familial breast cancer patients and at risk individuals were previously investigated for BRCA1 and BRCA2 mutations and some were positive for BRCA1/2 mutations." (PMID 24906410, 2014). "This indicates that cancer-free females with WBC methylated BRCA1 have abnormal plasma protein expression profile with great similarities with that seen in plasma from the breast cancer cases." (PMID 25403427, 2014). "Metabolism-related transcriptomics and metabolomics were combined to explore BRCA1-induced metabolic reprogramming of breast cancer cells." (PMID 25010005, 2014). "In this important study, the presence of BRCA1 gene expression was examined in 374 sporadic breast cancer patients." (PMID 25051360, 2014). "Mutations in BRCA1 and BRCA2 genes are associated with predisposition to breast cancer; hence we have screened both the cell lines for mutations/ polymorphisms in these genes." (PMID 24502646, 2014). "Given the reported low frequency of mutations in BRCA1 and BRCA2 in Sudanese breast cancer patients, the methylation status of six tumor suppressor genes was investigated using methylation specific PCR." (PMID 24607238, 2014). "Our results indicate that the p.R215W mutation in the HCC1395 breast cancer cell line impairs NBN function, making this cell line a potentially useful cellular model for studying defective NBN protein within a mutant BRCA1 background." (PMID 24928521, 2014). "Our data suggests that miR-638 elicits differential efficacy by silencing or inducing the expression of BRCA1 in different breast cancer cell lines." (PMID 25228385, 2014). "Why BRCA1 is largely a breast and ovarian cancer susceptibility gene, why males are largely protected from BRCA1 cancer and how an ostensibly normal mammary epithelial cell in a BRCA1 mutation carrier (BRCA1mut/+) gives rise to breast cancer cells are largely unknown." (PMID 25400221, 2014). "In the case of miR-182, which has been described to be upregulated in breast carcinoma, to target specifically BRCA1 gene and to be involved in the resistance to PARP-1 inhibitors, we identified a relationship between miR-182 expression and clinical outcome." (PMID 25369070, 2014). "This 17q25.3 gain was detected in 90% of the BRCA1-mutated BC (86% of the mutated TNBC and 100% of the mutated non-TNBC) in our cohort and was also highly recurrent in the BRCA1-mutated breast cancer of the TCGA cohort." (PMID 25416589, 2014). "TNBC accounts for 12–17% of all breast cancers and shares similarities with basal-like breast cancer (BC), claudin-low BC, and BRCA1-related disease." (PMID 25389442, 2014). "Overall, the Breast cancer information core (BIC) database (research.nhgri.nih.gov/bic/) has recorded 1,639 and 1,853 distinct mutations, polymorphisms, and variants in the BRCA1 and BRCA2 genes, respectively." (PMID 23354980, 2013). "We used breast cancer cell lines HCC1937 (BRCA1−/−) and MDAMB231 (BRCA+/+) as controls and HeLa cell lines silenced or not for BRCA1 and BRCA2." (PMID 23761435, 2013). "These relationships are well demonstrated by the observation that the gene products of the early onset breast cancer genes BRCA1 and BRCA2, whose germline loss or mutation confers a near 80% risk of developing breast cancer, are themselves DNA repair proteins." (PMID 23762064, 2013). "In a population-based study, mutations in the two predominant breast cancer susceptibility genes, BRCA1 and BRCA2, accounted for approximately 20% of familial breast cancer diagnoses." (PMID 24137204, 2013). "Ataxia telangiectasia presents with a significant increased all-cause cancer risk consistent with its critical repair role and inherited HR protein BRCA1 and BRCA2 mutants strongly predispose toward breast cancer, prostate, and colon cancer." (PMID 24364026, 2013).
breast cancer (continued). "In present work, we clearly show that the breast cancer cells harboring various types of defective BRCA1 are more sensitive to cucurbitacin B than the wt-BRCA1 possessed cells." (PMID 23393598, 2013). "Although some genes have been identified such as BRCA1/2 for breast cancer and APC for colorectal cancer that account for a small proportion of these familial cancers the search for additional highly penetrant genes has largely been unsuccessful." (PMID 23907184, 2013). "High-penetrance breast cancer susceptibility genes, such as BRCA1 and BRCA2, explain only a small fraction of breast cancers in the general population because of their low mutation rates." (PMID 23976942, 2013). "Five genes are found activated in the mouse Brca1-/- tumor dataset and the three breast cancer datasets, predominantly in basal-like cancers; statistical analysis indicated significant enrichment of these genes." (PMID 23506684, 2013). "Approximately 1 in 800 people carries a BRCA1 (breast cancer 1, early onset) mutation and approximately 1 in 500 people carries a BRCA2 (breast cancer 2, early onset) mutation." (PMID 23885284, 2013). "The data presented here support a role for BRCA1 in the pathogenesis of sporadic and inherited breast cancers." (PMID 23855721, 2013). "The treatment with cucurbitacin B is more effective in BRCA1 defective breast cancer cells than in the wild type BRCA1 breast cancer cells." (PMID 23393598, 2013). "miR-146 and miR-146b-5p were validated as regulator of BRCA-1 and found up-modulated in TN and basal-like breast cancer cell lines, being responsible for BRCA1-mediated effects on proliferation and homologous recombination." (PMID 24284394, 2013). "Median age of diagnosis was 42 years among BRCA1, 43.5 years among BRCA2 mutation carriers, and 61 years for sporadic breast cancer patients." (PMID 23704984, 2013). "The average age for the onset of breast cancer in PALB2 c.1592delT carriers is 53.1 years, which is somewhat higher than in Finnish BRCA1/BRCA2 mutation carriers (45.2/47.4 years), but considerably lower than in sporadic patients (58.0 years)." (PMID 23941127, 2013). "When BRCA1 mutations occur, the DNA repair function is not regulated and there is an inherited correlation between the BRCA1 gene and the pathogenesis of breast cancer." (PMID 23426861, 2013). "When BRCA1 expression is abrogated specifically in the luminal progenitor subpopulation, mice develop mammary tumours that phenocopy human BRCA1 breast cancers." (PMID 23863842, 2013). "Clinical studies on breast cancer demonstrated an unique sensitivity of BRCA1-accociated tumors to cisplatin." (PMID 23548133, 2013). "In breast cancer xenografts, therapy resistant triple-negative cancer lost BRCA1 promoter methylation and re-expressed the BRCA1 protein." (PMID 24265793, 2013). "Some insight was gained by a study demonstrating that BRCA1 is an important transcriptional regulator, which modulates the translational efficiency of approximately 7% of the mRNAs expressed in human breast cancer cell line MCF-7." (PMID 24321281, 2013). "All possible nucleotide substitutions were seen within 96 possible trinucleotide sequence contexts without predominant patterns of particular trinucleotides, which was a characteristic signature of both BRCA1- and BRCA2-associated breast cancers." (PMID 24265793, 2013).